POTEA (POTE ankyrin domain family member A (gene/pseudogene))
Synonyms: POTE-8; A26A1; POTE8; CT104.3
Gene: Protein-coding gene on chromosome 8 (43,292,483 to 43,363,518, forward strand). Ensembl gene ENSG00000188877.
Genetic constraint (gnomAD): Missense variants: 480 observed, 400.48 expected, observed/expected ratio (o/e) 1.2, 90% interval 1.11 to 1.29. Synonymous variants: 175 observed, 140.32 expected, observed/expected ratio (o/e) 1.25, 90% interval 1.1 to 1.41.
Homologues: Orthologues: chimpanzee POTEA (68% identical), mouse Potefam1 (27% identical), rat Potefam1 (26% identical), mouse Ankrd7 (15% identical), rat A630010A05Rikl (15% identical), mouse Potefam3c (12% identical), mouse Potefam3d (12% identical), mouse Potefam3a (12% identical), mouse Potefam3b (12% identical), mouse Potefam3e (12% identical), mouse Potefam3f (10% identical). Paralogues in human: POTEF (58% identical), POTEE (58% identical), POTEI (58% identical), POTEJ (56% identical), POTEB3 (53% identical), POTED (52% identical), POTEB (51% identical), POTEB2 (51% identical), POTEC (48% identical), POTEH (44% identical), POTEM (44% identical), POTEG (43% identical), and 2 more.
Diseases named in the same sentence as POTEA in open-access papers:
POTEA is named in the same sentence as 1 disease in open-access papers, as found by Europe PMC text mining. Sharing a sentence is not in itself a finding about the gene and the disease. The quoted sentences say what the papers report.
cancer (1 paper, 2018). A tumor composed of atypical neoplastic, often pleomorphic cells that invade other tissues. "This variant is located in the exonic region of POTEA gene, member of a highly homologous gene family expressed in a wide variety of human cancers (colon, lung, breast, ovary and pancreas)." (PMID 29547645, 2018).